BRCA1 (BRCA1 DNA repair associated)
Diseases named in the same sentence as BRCA1 in open-access papers (continued):
Sharing a sentence is not in itself a finding about the gene and the disease.
tumor (continued). "Furthermore, since BRCA1 patients maintain a statistically significant OS advantage, even after matching each case to four controls for age and tumour grade and disease stage, this result is very important in terms of its practical value, because all confounders have been removed." (PMID 20219108, 2010). "Thus, given the importance of BRCA1 to genomic stability, methylation of BRCA1 may ultimately affect the tumor suppressor ability of BRCA1." (PMID 20614009, 2010). "If the tumour is ER-negative but not TN, however, the probability of carrying a BRCA1 mutation is even less relative to when the tumour is ER-negative but of unknown TN status." (PMID 20482762, 2010). "Additionally, two other sporadic tumours within this subgroup displayed loss of BRCA1 protein expression without detectable hypermethylation of the BRCA1 gene promoter and both of these tumours were CK5/6 positive." (PMID 19589159, 2009). "In contrast, 60% of the ESR1-negative tumours (group B), which show the highest expression of NFκB2 and RELB, harboured missense mutations in BRCA1, which could produce aberrant proteins but conserving some activities such as the capacity to activate the NFκB machinery." (PMID 19826428, 2009). "The combination of tumor suppressors inactivated in this study failed to yield epithelial cancers, indicating that further analyses are needed to determine the mechanisms by which BRCA1 mutations cause transformation of the ovarian epithelium." (PMID 20046869, 2009). "Thus, the loss of PHD3 expression induced by the BRCA1/STAT dysfunction may be a mechanism specific to BRCA1 tumours." (PMID 19724277, 2009). "Thus, BRCA1-Δ11 may compensate for some of the functions of full-length BRCA1 during embryogenesis, but is unable to fully execute the functions of full-length BRCA1 in maintenance of genomic stability and tumour suppression." (PMID 19904273, 2009). "Censoring out other expressions of the same genetic defect, is, however, informative censoring if the question is prognosis in a BRCA1 mutation carrier (which may not be identical to prognosis of the first tumour detected)." (PMID 19366445, 2009). "Thus, in contrast to other models, such as MMTV-PyMT and MMTV-wnt1, in which pooling individual mouse tumors can generate sufficient material for basic and translational studies, Brca1 tumors will need to be analyzed individually and these studies are limited by the size of each original tumor." (PMID 18241344, 2008). "BRCA1 null tumour cells may therefore be intrinsically resistant to these agents." (PMID 17697367, 2007). "In addition to its interaction with BRCA1, there is indirect evidence to suggest that BCoR-L1 may behave as a tumour suppressor." (PMID 17697391, 2007). "The patient carrying this tumor was negative to the molecular screening, as those reported in other series, ruling out the possibility that BRCA1/2 mutations may confer a significantly increased risk of developing this peculiar MBC histotype." (PMID 16764716, 2006). "However, a recent report showing high levels of BRCA1 expression and a low frequency of BRCA1 promoter methylation in basal-like sporadic tumours suggests that this might be more complex." (PMID 16846527, 2006). "Familial cases without BRCA1/2 mutations had tumours of lower grade than the other groups." (PMID 15642173, 2005).
tumor (continued). "Dysfunction of homologous recombination genes, such as BRCA1 and BRCA2, contributes to genomic instability and the development of more aggressive tumor clones." (PMID 41899427, 2026). "Paired tumor and blood samples from 136 TNBC patients (SCANDARE, NCT03017573) were analyzed for BRCA1 methylation, genomic alterations, HRD and outcomes." (PMID 41654537, 2026). "Initially identified for its role in BRCA1 regulation, BAP1 is now known as an independent tumor suppressor involved in DNA damage repair, cell cycle regulation, and cell growth." (PMID 41551629, 2026). "Genomic stability markers, such as BRCA1 and BRCA2, alongside luminal regulators like GATA3, decline progressively with both advancing age and tumor aggressiveness, reaching their lowest levels in TNBC." (PMID 41889413, 2026). "Machine learning (ML) models can predict resistance to endocrine therapies or HER2-targeted agents based on genomic alterations (e.g., BRCA1/2, PIK3CA) and tumor microenvironmental factors." (PMID 40941035, 2025). "In both HGSOC with HRD phenotype and BRCA1 mutant TNBC, CD274 (PD-L1) expression on tumor cells is also upregulated." (PMID 40830526, 2025). "Analysis of TCGA database (accession number: phs000178) revealed increased PSI values for ACTA2, AREG, BRCA1, DDX5, MSH6, and PARP1 in tumor tissues compared to adjacent tissues." (PMID 39773744, 2025). "Mechanistically, erlotinib enhances gemcitabine induced tumor cell apoptosis by inhibiting the EGFR signaling pathway and downregulating BRCA1 mediated DNA repair ability." (PMID 41293424, 2025). "To address the challenges of CNV detection in such samples, we applied ddPCR to analyze BRCA1 exon 22 and BRCA2 exon 27 using DNA derived from both blood and frozen tumor samples." (PMID 40725150, 2025). "Unlike traditional PCR methods, ddPCR offers absolute quantification of target molecules, enabling precise detection of BRCA1/2 CNV deletions with high sensitivity and specificity, even in tumor DNA highly contaminated by normal cells." (PMID 40725150, 2025). "In conclusion, our results demonstrate that the effect of BM-MSCs-exo on CRT is highly dependent on tumor context, likely influenced by factors such as HPV genotype, histological subtype, and intrinsic DNA repair capacity, particularly BRCA1 activity." (PMID 40732337, 2025). "Interestingly, a third patient had a loss of somatic BRCA1 expression without identification of an underlying germline variant, suggesting other patients may have tumor landscapes susceptible to similar therapeutic strategies." (PMID 40072012, 2025). "Tumor sections from CBPt-treated animals also presented with higher levels of HRR-related proteins, including RAD51 and BRCA1, whereas this increase was reduced in the AQB + CBPt group." (PMID 41353219, 2025). "BRCA1 and BRCA2 are key tumor suppressors, and they are essential for homologous recombination repair (HRR) where BRCA1 promotes DNA end processing and BRCA2 assists RAD51 loading for error-free repair of double-strand breaks." (PMID 41373752, 2025). "This opens the door to exploring 4-MU as a tumor reprogramming agent in clinical trials, particularly for TNBC patients with a low BRCA1/2 expression." (PMID 41373491, 2025). "In this study, we performed ddPCR to quantify the CNVs of BRCA1 and BRCA2 in the same exons as detected by MLPA, aiming to clarify the limitations in detecting DNA tumor heterogeneity, particularly in cases with ambiguous results." (PMID 40725150, 2025). "Lastly, after confirming HA reduction in all three cell lines, we assessed its impact on tumor volume, CD44 (HA’s main receptor and potential BRCA regulator), HYAL1 (which responds to HA changes), and BRCA1/2 expression." (PMID 41373491, 2025). "The cellular levels of BARD1 and its interaction with BRCA1 are critical for the heterodimeric function of the BRCA1-BARD1 complex in HR repair and tumor suppression." (PMID 41009605, 2025).
tumor (continued). "Recent studies suggest that BRCA1 and BRCA2 expression patterns vary with tumor grade, potentially reflecting their roles in tumor progression." (PMID 40224184, 2025). "BRCA1 PV carriers were significantly more likely to be diagnosed with TNBC and higher Ki-67 (>10%) (p < 0.001), indicating a more aggressive tumor type." (PMID 40422528, 2025). "Compared to women with BRCA1 and BRCA2 PVs, our data indicate that women with PJS have more favorable tumor characteristics." (PMID 40317347, 2025). "BRCA1 and BRCA2 are tumour suppressor genes responsible for homologous recombination repair of DNA lesions, particularly double-stranded DNA breaks." (PMID 40447784, 2025). "BRCA1 and BRCA2 are essential tumor suppressor genes that play critical roles in the homologous recombination repair (HRR) pathway, responsible for the accurate repair of DNA double-strand breaks." (PMID 40936705, 2025). "Accordingly, in both BRCA1/2-mutant and BRCA1/2-WT xenograft models, treatment with CCL5 neutralizing antibodies significantly inhibits PARPi-induced CAFs and decreases tumor volumes." (PMID 40830526, 2025). "This study highlights the novel finding that 5-formamidoimidazole-4-carboxamide ribotide suppresses BRCA1 expression by inhibiting METTL1-mediated m7G modification, ultimately leading to the inhibition of HGSOC cell proliferation and tumor growth." (PMID 41430564, 2025). "BRCA1 and BRCA2 carriers were characterized by distinct patient, tumor, and treatment characteristics and a different pattern and risk of DFS events over time." (PMID 39993249, 2025). "BRCA1 and BRCA2 are well-known tumor suppressors involved in DNA repair, cell cycle regulation, and maintaining genomic stability, particularly under stress conditions like replication, meiosis, or mitosis." (PMID 41373491, 2025). "We propose this increased caspase expression is used to support tumor stress adaptation, through enhanced PARP1 activity, autophagy, and DDR signaling, and may be a targetable vulnerability, particularly in the context of BRCA1 or other potential synthetic lethal mutations identified here." (PMID 39982959, 2025). "qPCR analysis of the tumor tissue demonstrated that the expressions of DNA damage marker genes (TP53BP1, PARP1, and BRCA1), cGAS, STING, SEI1, and PD‐L1 were increased in melphalan or bortezomib treated mice." (PMID 40135791, 2025). "The BRCA1 and BRCA2 genes are tumor suppressors involved in DNA repair through homologous recombination, essential for maintaining chromosome integrity as part of the ATM-mediated DNA repair pathway." (PMID 41077566, 2025). "The findings largely validated previous reports highlighting the importance of tumor suppressor genes such as ATM, BRCA1, BRCA2, and PALB2 for a limited number of tumor types." (PMID 40072281, 2025). "PDGFRB signaling in the tumor microenvironment promotes epithelial-mesenchymal transition (EMT) and is inhibited by BRCA1, making it a significant therapeutic target, particularly in BRCA1-deficient TNBC." (PMID 41017855, 2025). "Bedsides, in BRCA1/2 wild-type TNBC models, combined inhibition of WEE1 and PARP (Olaparib) markedly suppresses tumor growth and reshapes the tumor microenvironment." (PMID 40949156, 2025). "For the BRCA1 and BRCA2 tumor suppressor genes, a 20% wild-type expression of the full-length transcript has been designated as sufficient to prevent tumorigenesis by current VCEP specifications." (PMID 39780207, 2025).
tumor (continued). "Studies suggest that DDR processes, including BRCA1 activity, are activated during the early stages of OSCC to mitigate genomic instability and support tumor survival." (PMID 40224184, 2025). "Among tumor samples, those without BRCA1 mutations showed stronger hypomethylation (t-test, P < 10− 100 for all comparisons), suggesting the extent of global hypomethylation may vary with the molecular characteristics of the tumor." (PMID 41168225, 2025). "In addition, the finding that BRCA1 hypermethylation has also been found in benign breast lesions (that can later evolve into cancer) and normal tissues adjacent to the tumor site might suggest a potential use of its epigenetic silencing as an early biomarker of genomic instability." (PMID 40141248, 2025). "We evaluated OFD1 expression in human tumor tissues and peri-cancerous tissues surgically resected from 90 PDAC patients using IHC with validated OFD1 and BRCA1 antibodies." (PMID 40764600, 2025). "GATA binding protein 3 (GATA3) is a nuclear zinc-finger TF that functions downstream of BRCA1 to promote DDR and suppress dedifferentiation in BC, acting as a tumor suppressor." (PMID 39860065, 2025). "The overexpression of UHRF1 repressed the transcription of such tumor-suppressor genes as CDKN2A, BRCA1, and CDH1 through DNMT1-mediated DNA methylation." (PMID 38725075, 2024). "Up to date, the relevance of the BRCA1/BARD1 E3 activity for DSBs repair, tumor suppression, and resistance to PARP inhibitors and platinum-based compounds is still controversial." (PMID 38769345, 2024). "The most common tumor types were ovarian (n = 23), breast (n = 15), pancreatic (n = 14), and prostate (n = 14); the most frequent enrollment genes were ATM (n = 38), BRCA1 (n = 28), BRCA2 (n = 15), SETD2 (n = 10), and CDK12 (n = 7)." (PMID 38710487, 2024). "BRCA1 and BRCA2-defective tumors are intrinsically sensitive to PARP inhibitors, both in tumor models in vivo and in the clinic, contrasting to normal cells with an intact HR." (PMID 39684238, 2024). "The inter-group expression difference analyses for tumor genes implied that APC, ATM, BARD1, BRAF, and BRCA1 gene expression varied among patients in these two groups." (PMID 38338834, 2024). "Although we expected more tumor driver and HRD genes in the hallmarks, such as BRCA1/2, we will further investigate the other genes for their role in PARPi resistance." (PMID 38927686, 2024). "Additionally, BRCA Ashkenazi Jewish founder mutations (BRCA1 c.68_69delAG, BRCA1 c.5266_5267insC, or BRCA2 c.5946delT) were detected at similar rates across all subgroups, highlighting the need for further research to understand their role in tumor response to PARP inhibitors." (PMID 39272683, 2024). "For example, the loss of the 3p chromosome arm disrupts critical genes like VHL, PBRM-1, BRCA1, and MTOR that act as tumor suppressors." (PMID 39796121, 2024). "BARD1 and BRCA1 form a heterodimer through the interaction of their RING-finger domains; this heterodimer plays crucial roles in several tumor-suppressive functions related to DNA repair and apoptosis." (PMID 38485918, 2024). "Demographic information and tumor characteristics for those with and without pCR were statistically significant by age at diagnosis (P = .04) and median Ki-67 (0.004), while other baseline characteristics such as BMI, race/ethnicity, and BRCA1/2 mutation status were comparable." (PMID 38656345, 2024).
tumor (continued). "For instance, the “BRCA1 in DRR” pathway and the “Tumor microenvironment (TME)” pathway were positively and negatively associated with the Th2 infiltrate, respectively." (PMID 38672668, 2024). "However, we could not draw definitive conclusions of the relationship between SOSTDC1 protein level and BRCA1 mutation since there was no available information on BRCA1 status in the TNBC patient tumor samples we used in this study." (PMID 38864559, 2024). "Germline BRCA1 and BRCA2 alterations increase the probability to develop BC and other tumor types, including ovarian, pancreatic, prostate, colorectal cancer and melanoma." (PMID 39062721, 2024). "To further validate these findings, we conducted qPCR analysis to assess the expression of ESR1, BRCA1, CTNNB1, and BAX in tumor tissue." (PMID 39045563, 2024). "BRCA1 and BRCA2 are both tumor suppressor genes critical to maintaining genome integrity during DNA replication." (PMID 38544832, 2024). "This included an artesunate-resistant cell line, OV-90, a BRCA1-mutant cell line, UWB1.289, and a patient-derived tumor organoid line (UK1254)." (PMID 38610999, 2024). "The tumor suppressor genes BRCA1 and BRCA2 are involved in essential cellular functions necessary for cell replication and DNA synthesis, playing a crucial role in DNA repair and tumor suppression." (PMID 39575418, 2024). "Guidelines have been developed for the identification of gP/LPVs in BRCA1/2 genes on the basis of tumor-only CGP results and for the evaluation of the appropriateness of performing germline reflex BRCA1/2 testing." (PMID 39363506, 2024). "In tamoxifen-resistant tumor cells, the activation of the PI3K/AKT pathway led to a significant increase in BARD1 and BRCA1 protein expressions via increased estrogen independent activation of ERs." (PMID 38672654, 2024). "Anti-angiogenic agents down-regulate HR genes such as BRCA1/2 and RAD51 through inducing hypoxia in the tumour microenvironment and interactions with other transcriptional repressors." (PMID 39135999, 2024). "IHC analysis and western blot analysis of tumor xenograft samples also showed that the levels of γH2AX and cleaved caspase-3 were obviously upregulated, whereas PIK3R1 and BRCA1 levels were decreased upon circPLPP4 inhibition." (PMID 38184597, 2024). "BRCA1 and BRCA2 are tumour suppressor genes that play a critical role in the repair of double-strand DNA breaks through HR." (PMID 39360040, 2024). "These off‐tumor incidental findings are not only common in moderately penetrant genes such as CHEK2, but have been described for highly‐penetrant genes such as BRCA1/2, as well." (PMID 38898688, 2024). "BRCA1 and HDAC1 exhibited significantly elevated expression in tumor samples, while RANGAP1 demonstrated significantly decreased expression in tumor samples." (PMID 38801243, 2024). "BRCA1 is located in chromosome 17q21, whereas BRCA2 is located in chromosome 13q12, which are both autosomal dominant tumor suppressor genes involved in DNA damage repair prior to cell replication." (PMID 38297203, 2024). "Considering a distinction for neoplasm, among the 100 MBC patients, 16 were carriers of germline PVs in BRCA2 and only one in BRCA1, whereas 80 were BRCA1/2-wild-type." (PMID 38974244, 2024). "IGF-1 increases BRCA1 gene expression and enhances BRCA1 promoter activity, indicating a complex, bidirectional interplay between IGF-1 pathways and BRCA1-mediated tumor protective pathways." (PMID 39273251, 2024). "BRCA1 and BRCA2 are tumour suppressor genes responsible for repairing double-strand DNA breaks via the homologous recombination repair (HRR) pathway." (PMID 39682099, 2024). "PALB2 showed outlier high expression (99th percentile) as did other genes involved in HR including BRCA1 (94th percentile), BRCA2 (100th percentile), and HERC2 (100th percentile) in this tumor." (PMID 38755180, 2024).